ACP6 (acid phosphatase 6, lysophosphatidic)
Description:
Hydrolyzes lysophosphatidic acid (LPA) containing a medium length fatty acid chain to the corresponding monoacylglycerol. Has highest activity with lysophosphatidic acid containing myristate (C14:0), monounsaturated oleate (C18:1) or palmitate (C16:0), and lower activity with C18:0 and C6:0 lysophosphatidic acid.
Synonyms: ACPL1; LPAP; PACPL1
Tractability: Small molecule: a structure with a bound ligand is known. PROTAC: its protein half-life has been measured.
Gene: Protein-coding gene on chromosome 1 (147,629,652 to 147,670,531, reverse strand). Ensembl gene ENSG00000162836.
Subcellular location: Mitochondrion
Pathways (Reactome):
Metabolism: Synthesis of PA
Gene Ontology:
Molecular function: lysophosphatidic acid phosphatase activity
Biological process: lysobisphosphatidic acid metabolic process; phospholipid metabolic process; phosphatidic acid biosynthetic process
Cellular component: cytoplasm; mitochondrion; mitochondrial matrix
Genetic constraint (gnomAD): Loss-of-function variants: 46 observed, 44.79 expected, observed/expected ratio (o/e) 1.03, 90% interval 0.81 to 1.31. The upper end of that interval is the gene's LOEUF score, 1.31, which puts it in group 5 of 6, group 1 being the genes least tolerant of losing a copy. Missense variants: 442 observed, 481.98 expected, observed/expected ratio (o/e) 0.92, 90% interval 0.85 to 0.99. Synonymous variants: 159 observed, 187.56 expected, observed/expected ratio (o/e) 0.85, 90% interval 0.74 to 0.97.
Homologues: Orthologues: chimpanzee ACP6 (99% identical), macaque ACP6 (95% identical), rabbit ACP6 (84% identical), dog ACP6 (82% identical), pig ACP6 (82% identical), guinea pig ACP6 (80% identical), mouse Acp6 (75% identical), rat Acp6 (68% identical), tropical clawed frog acp6 (52% identical), zebrafish acp6 (41% identical), Caenorhabditis elegans F26C11.1 (20% identical), Caenorhabditis elegans acp-3 (19% identical), and 11 more. Paralogues in human: ACP2 (25% identical), ACP4 (24% identical), ACP3 (23% identical), PXYLP1 (20% identical), FRA10AC1 (10% identical).
Diseases named in the same sentence as ACP6 in open-access papers:
ACP6 is named in the same sentence as 16 diseases in open-access papers, as found by Europe PMC text mining. Sharing a sentence is not in itself a finding about the gene and the disease. The quoted sentences say what the papers report.
esophageal squamous cell carcinoma (3 papers, 2019 to 2023). Esophageal squamous cell carcinoma (ESCC) is a type of esophageal carcinoma (EC) that can affect any part of the esophagus, but is usually located in the upper or middle third. "On the other hand, decreased expression of ACP6 was found to contribute to increased cell mortality and disease progression in high-grade serous ovarian cancer and esophageal squamous cell carcinoma." (PMID 37228491, 2023). "Two studies have revealed the down-regulation of ACP6 in esophageal squamous cell carcinoma and ovarian cancer as well as the impact of dys-regulated ACP6 on cancer progression." (PMID 36456931, 2022).
hepatocellular carcinoma (2 papers, 2022 to 2023). A malignant tumor that arises from hepatocytes. "It has been recently demonstrated that overexpression of ACP6 in hepatocellular carcinoma tissue was positively correlated with clinical progression and worse overall survival of examined patients." (PMID 37228491, 2023). "No investigations have been conducted on ACP6 in hepatocellular carcinoma (HCC) up to date." (PMID 36456931, 2022).
ovarian carcinoma (2 papers, 2019 to 2022). A malignant neoplasm originating from the surface ovarian epithelium. "Downregulation of ACP6 in ovarian cancer cells was necessary and sufficient to support HGSOC proliferation, adhesion, migration, and invasion." (PMID 30914657, 2019). "ACP6 was highly expressed in normal fallopian tube epithelial tissues compared to normal ovaries and ovarian cancer." (PMID 30914657, 2019).
serous ovarian cancer (2 papers, 2019 to 2023). "In addition to promoting progression in in vitro and in vivo model systems, ACP6 expression also correlated with overall survival in serous ovarian cancer patients." (PMID 30914657, 2019).
Cerebral visual impairment (1 paper, 2018). A form of loss of vision caused by damage to the visual cortex rather than a defect in the eye. "Likewise, pathogenic variants in ACP6 have been recently identified in children with cerebral visual impairment, which results from the impairment in projection and/or interpretation of the visual input in the brain, and which usually co-occurs with intellectual disability." (PMID 29922639, 2018).
esophageal cancer (1 paper, 2019). A primary or metastatic malignant neoplasm involving the esophagus. "In esophageal cancer, decreased ACP6 levels contribute to tumor growth and lymph node metastasis and ACP6 could have potential tumor suppressive functions." (PMID 30914657, 2019).
viral disease (1 paper, 2023). "Larvae infected with any of the viruses had no obvious changes in phenotype before 3 days p.i., including death and color changes (melanization) known to be associated with viral disease, but a few deaths occurred in the AcMNPV-Rep- and Acp6.9-chiA/polh-cath-infected larvae." (PMID 36851718, 2023). "We previously determined that CHIA overexpression by Acp6.9-chiA did not compromise virus infection kinetics relative to AcEGFP and AcMNPV." (PMID 36851718, 2023).
cancer (5 papers, 2019 to 2024). A tumor composed of atypical neoplastic, often pleomorphic cells that invade other tissues. "ACP5 and ACP6 are unfavourable prognostic genes to tumour growth and immune system evasion, highlighting their role in cancer progression." (PMID 39457550, 2024). "The function of ACP6 in cancer-related inflammation and CRC tumorigenesis needs to be further investigated." (PMID 37228491, 2023). "Because tumor microenvironment played essential roles in regulating various biological events of human cancers, we analysed the correlation between ACP6 expression and infiltration level of a wide range of immune cells in HCC." (PMID 36456931, 2022). "Acid phosphatase type 6 (ACP6) is a mitochondrial lipid phosphate phosphatase that played a role in regulating lipid metabolism and there is still blank in the clinico-pathological significance and functional roles of ACP6 in human cancers." (PMID 36456931, 2022). "Downregulation of ACP6 in HeyA8 cells increased cancer cell proliferation, adhesion, migration and invasion." (PMID 30914657, 2019). "ACP6 expression may serve as novel clinical biomarker indicating the clinical development of HCC and ACP6 might be potential target of anti-cancer effect by NC in HCC." (PMID 36456931, 2022). "Moreover, ACP6 was reduced in CRC patients with cancer-related inflammation." (PMID 37228491, 2023). "For reducing systematic errors and properly assessing the differential expression of ACP6 between HCC and non-cancer liver tissues, we rigorously processed all included datasets through removal of batch effect and normalization." (PMID 36456931, 2022). "ACP6 displayed significant overexpression in HCC samples (standard mean difference (SMD) = 0.69, 95% confidence interval (CI) = 0.56–0.83) and up-regulated ACP6 performed well in screening HCC samples from non-cancer liver samples." (PMID 36456931, 2022). "There is still blank in the clinico-pathological significance and functional roles of ACP6 in human cancers and no investigations have been conducted on ACP6 in HCC up to date." (PMID 36456931, 2022).
tumor (4 papers, 2017 to 2024). "Using mouse models of metastasis, we established that attenuation of ACP6 expression was associated with increased tumor burden." (PMID 30914657, 2019). "Consistent with the in vitro functional experiments, the knockdown of ACP6 significantly increased both tumor burden and metastatic spread, while the overexpression of ACP6 reduced tumor burden and metastasis in both HeyA8 and Tyk-nu models." (PMID 30914657, 2019). "We next investigated if ACP6 expression predicted patient outcome or tumor grade." (PMID 30914657, 2019).
infection (2 papers, 2019 to 2023). The state of being infected such as from the introduction of a foreign agent such as serum, vaccine, antigenic substance or organism. "Infection with the dual reprogrammed Acp6.9-chiA/polh-cath virus, in which chiA is expressed under the p6.9 promoter and v-cath under the polh promoter, led to earlier larval death and liquefaction relative to infection with AcEGFP, Acp6.9-chiA, or AcMNPV-Rep." (PMID 36851718, 2023). "Therefore, we compared the kinetics of Acp6.9-chiA/polh-cath infection of cultured cells to that of AcEGFP, AcMNPV-Rep, and Acp6.9-chiA to determine if CHIA and V-CATH enzyme levels were deleterious to the Acp6.9-chiA/polh-cath infection cycle." (PMID 36851718, 2023). "This suggested that Acp6.9-chiA/polh-cath overexpression of v-cath during larval infection resulted in an increase of extracellular V-CATH enzyme capable of prematurely degrading host tissues, as compared to infection with AcMNPV-Rep, and corroborating our earlier report." (PMID 36851718, 2023).
ACP6 also shares sentences with these, for which no sentence is quoted: bladder cancer (1 paper); congenital hypothyroidism (1); genetic diseases (1); hepatitis B (1); imperforate anus (1); Intellectual disability (1).